SCARNA18B (small Cajal body-specific RNA 18B)
Gene: Small nucleolar RNA gene on chromosome 1 (193,057,281 to 193,057,415, reverse strand). Ensembl gene ENSG00000238754.
Gene Ontology:
Biological process: RNA processing
Cellular component: nucleolus
Homologues: Orthologues: chimpanzee SCARNA18B (99% identical), macaque SCARNA18B (97% identical), rabbit SCARNA18B (90% identical), guinea pig SCARNA18B (88% identical), mouse Gm25663 (87% identical), rat Scarna18b (82% identical). Paralogues in human: SCARNA18 (88% identical).